IL7 (interleukin 7)
Diseases named in the same sentence as IL7 in open-access papers (continued):
Sharing a sentence is not in itself a finding about the gene and the disease.
cancer (continued). "A similar T cell effect was reported in several phase I clinical trials with minimal toxicities in which IL-7 was administered subcutaneously in the patients of cancer and HIV infection." (PMID 24465710, 2014). "Our findings justify further evaluation of combining IL-7 and chemotherapy as a novel experimental cancer therapy." (PMID 24465710, 2014). "The beneficial effect of administration of IL-7 on T cell homeostasis in patients with refractory cancer, in SIV infected macaques and HIV infected individuals has been shown through several early trials and observational studies." (PMID 24853554, 2014). "The observation of a thymopoietic effect confirmed earlier data sets produced in IL-7 treated monkeys as well as early thymic assessments performed on cancer patients." (PMID 22383042, 2012). "This better supports and justifies the current therapeutic approach utilized in treating cancer patients with IL-7." (PMID 22383042, 2012). "Together, non-lymphopenic patients with chronic viral or bacterial infections or with cancer can benefit from IL-7 treatment if it is combined with an additional therapy utilized to create conditions favorable to the emergence of an immune response." (PMID 22383042, 2012). "For example, cancer patients treated with IL-7 experienced marked increases in peripheral CD4+ and CD8+ T cells, resulting in a rejuvenated circulating T-cell profile." (PMID 22369276, 2012). "IL-2, IL-7, IL-15 and IL-21, sharing a common receptor γ chain (c-γ), control T lymphocyte homeostasis and proliferation and play major roles in regulating cancer-immune system interactions." (PMID 21943235, 2011). "The bone-aggressive cancer cells were positive for IL-7 staining both in the mice model and in human biopsies." (PMID 20067635, 2010). "First results of recombinant IL-7 therapy as immunomodulation in persons with refractory cancer have recently been published." (PMID 19096522, 2008). "Our study focused on IL-7 involvement in the spontaneous osteoclastogenesis occurring in cancer patients with osteolytic metastasis." (PMID 17205128, 2006). "To further study the involvement of TNF-α and RANKL we cultured cancer patients' PBMC in presence of IL-7 and a neutralizing anti-TNF-α antibody or osteoprotegerin (OPG) in different concentrations." (PMID 17205128, 2006). "The relative expression of IL-7 was seven-fold higher in B cells than in T cells in cancer patients." (PMID 17205128, 2006). "Therefore, IL-7 acts as both an immune modulator and an important component of the microenvironment that supports the cancer cell phenotype." (PMID 41597220, 2026). "Importantly, recombinant IL-7 has undergone clinical testing alone or alongside other immunotherapies to stimulate the antitumor activity of T cells in refractory cancers (NCT05075603, NCT04588038, NCT04710043)." (PMID 40957993, 2025). "Furthermore, a phase I clinical study showed that IL-7 increased the number of peripheral CD8+ T cells in advanced cancer." (PMID 40707961, 2025). "Given that exogenous IL-7 has been used as immunotherapy in cancer clinical trials to reconstitute the weakened immune system following aggressive treatments, our findings suggest that aerobic exercise could be an effective intervention to restore IL-7." (PMID 40642656, 2025). "However, IL-7 can be pro-tumorigenic, as it promotes cancer cell invasiveness by enhancing epithelial-mesenchymal transition." (PMID 40957993, 2025). "Additionally, IL-7 has been used as an ‘immune reconstitution’ agent to replenish T cells in immune-depleted cancer patients." (PMID 40957993, 2025). "Further study is needed to fully elucidate the role of IL-7 in cancer cachexia and to determine whether targeting the IL-7 signalling pathway is a viable therapeutic strategy for mitigating the devastating effects of cachexia in cancer patients." (PMID 38675377, 2024).
cancer (continued). "Additionally, recent advances in IL-7 in cancer immunotherapy and its potential for therapeutic applications are summarised and discussed." (PMID 38675377, 2024). "Enhanced levels of intracellular cytokines, such as interleukin 2(IL2), TNF-α, interferon-gamma (IFN-γ), and IL6, were observed within the memory subpopulation, indicating that IL7 may stimulate a memory immune response targeting cancer." (PMID 38289597, 2024). "Interleukin-7 (IL7) has long been theorized as a potential therapeutic agent in cancer treatment." (PMID 38554147, 2024). "Studies have shown that the effects of IL-7 on immune cell function and metabolism may contribute to cancer cachexia." (PMID 38675377, 2024). "Some studies have suggested that an inadequate supply of IL-7 in the secondary lymphoid organs might be insufficient to support the survival of activated T-cells, thereby aggravating cancer immunosuppression." (PMID 38256152, 2024). "There is also evidence that IL-7 may affect the mental state of cancer patients by influencing neurotransmitter levels, leading to psychological problems such as anxiety and depression, further reducing the patient’s quality of life." (PMID 38675377, 2024). "Previous studies have focused on T cells to explain the anti-cancer function of IL-7." (PMID 38424167, 2024). "Taken together, these findings suggest that IL7 may be a prime target for development as a cancer immunotherapy." (PMID 38554147, 2024). "Finally, IL-7 involves a variety of diseases, including autoimmune diseases, infections and cancers." (PMID 36936961, 2023). "IL7 has been reported to exhibit a dual role in cancer pathophysiology." (PMID 37958451, 2023). "Most cancer-related studies on IL7 and IL15 have focused on hematological malignancies." (PMID 38055067, 2023). "Thereinto, cytokines like IL-7 and IL-15 were listed among the top twelve immunotherapeutic agents with wide appeal to the immunotherapy and, by consensus, held particular promise for use in cancer therapy, as shown by the US National Cancer Institute in 2008." (PMID 38049832, 2023). "Furthermore, activation of the PI3K/AKT pathway by the IL-7 signaling pathway has been confirmed to play a pivotal role in cancer cell proliferation." (PMID 36106120, 2022). "The adjuvanticity of IL-7 has been verified to prolong the protective effects of vaccines by inducing the production of memory T and B cells, highlighting the potential to apply IL-7 as an adjuvant in combination with cancer vaccines to struggle against cancer cells via long-term memory protection." (PMID 36389666, 2022). "Moreover, 10 μl supernatants of transfected cancer cells were equivalent to 1 ng recombinant human IL-7 protein in promoting T cell proliferation." (PMID 36389666, 2022). "Notably, increased levels of IL-2, TNF-α, IFN-γ, and IL-6 were demonstrated in the memory subsets, indicating that IL-7 possesses the capability to stimulate the memory immune responses against cancers." (PMID 36389666, 2022). "Therefore, in this review, we summarized the biological function and mechanism of IL-7 and the signaling pathway of IL-7/IL-7R in T cells, as well as the performance of IL-7 as an adjuvant in combination with cancer vaccines in preclinical and clinical trials." (PMID 36389666, 2022). "Furthermore, we summarize and discuss the recent advances in the use of IL-7 and IL-7Rα as cancer immunotherapy tools and highlight their potential for therapeutic applications." (PMID 36142322, 2022). "However, the most common method to apply IL-7 as an adjuvant to enhance the antitumor effect of cancer vaccines in preclinical research was the injection of recombinant human IL-7 directly." (PMID 36389666, 2022). "Adjuvant effect of IL-7 in cancer vaccine treatment summarized from selective preclinical studies." (PMID 36389666, 2022).
cancer (continued). "Moreover, decreased levels of IFN-γ, GM-CSF, IL-1β, IL-7, IL-12, and IL-13 secretion were seen in cancer patients’ peripheral-blood derived sera when compared to those from the healthy individuals." (PMID 35203349, 2022). "Preclinical studies have proved that IL-7 could serve as an ideal adjuvant for cancer vaccines to combat cancers." (PMID 36389666, 2022). "Here, we also proposed some suggestions on how to utilize IL-7 as an adjuvant incorporated with cancer vaccines, including the form, dose, and chaperone cytokine of IL-7, which might be of value to researchers." (PMID 36389666, 2022). "Preclinical research highlighted that adjuvant IL-7, when combined with cancer vaccines, contributes to the generation and maintenance of T cell memory, which is the critical component to building up immune surveillance to restrict the recurrence and even metastasis of cancers." (PMID 36389666, 2022). "IL-7 is critical for the development, maintenance, and proliferation of T lymphocytes, highlighting its potential role as an adjuvant in the development of cancer vaccines." (PMID 36389666, 2022). "However, in current clinical trials, direct administration of human recombinant IL-7 subcutaneously as an adjuvant in combination with cancer vaccines is the preferred method." (PMID 36389666, 2022). "However, the adjuvant capability of IL-7 contributing to cancer vaccines was not only limited to inducing a short-term antitumor effect but also stimulating a long-term T cell memory against cancers." (PMID 36389666, 2022). "This could be explained because we studied cancer cells, which express Bcr/Abl as driver oncogene, obviating the need for exogenous cytokine signaling and making the cells IL-7 independent, while activating multiple endogenous signal transduction pathways." (PMID 36430839, 2022). "Previous studies have reported that cancer vaccines in combination with IL-7 induced a higher proportion of specific CD8+ and CD4+ memory T cells in mice models bearing tumors and improve the functionality of specific CD8+ memory T cells by enhancing their IFN-γ secretion." (PMID 36389666, 2022). "The rationale to utilize IL-7 as an adjuvant in combination with cancer vaccines was also proposed." (PMID 36389666, 2022). "In addition to IL-7’s application in infectious diseases, current understanding of cancer immunotherapy suggests that IL-7 therapy has great potential for cancer treatment." (PMID 34925323, 2021). "Our data provide a scientific rationale for evaluating IL-7 and IL-12 combination virotherapy in humans, and may further improve our understanding of cancer immunology." (PMID 33909103, 2021). "IL-7 modulates cell growth, apoptosis and modulates cancer lymphangiogenesis." (PMID 33892676, 2021). "We therefore addressed whether IL7/IL12 modified MSCs improve the CAR T cell anti-cancer cell attack by local application of MSCs and CAR T cells in a similar fashion by others." (PMID 32260097, 2020). "However, several reports have shown that IL-7 is able to antagonize the immunosuppressive network to improve immune function on cancer cells." (PMID 32698361, 2020). "Whereas the role of IL10 on cancer growth may be ambiguous we expect an overall beneficial impact of IL7/12 engineered MSC on a CAR T cell attack." (PMID 32260097, 2020). "The role of IL7 in cancer is still not fully understood, however our findings suggest that the Rho/MRTF pathway may negatively regulate expression of this cytokine." (PMID 31068602, 2019). "However, we also observed that IL-7 was locally overexpressed in gastrointestinal tumors from Stage 3/4 and N1 cancers to a greater degree than in tumors from Stage 1/2 and N0 cancers." (PMID 31185636, 2019). "The use of cytokines from the IL-2 family (also known as the common gamma chain cytokine family) such as IL-2, IL-7, IL-15 and IL-21 to activate the immune system of cancer patients is currently the one of the most important fields of cancer immunotherapy research." (PMID 31703694, 2019).
cancer (continued). "Based on the cell line results, we explored whether the expression levels of IL-7 and IL-7Rα are associated with the expression of EMT-related genes in cancer patient samples." (PMID 31061414, 2019). "This suggests that the reactivity to IL-7 may vary depending on the cancer origin or its derivatives." (PMID 31061414, 2019). "Background and objectives: Interleukin-7 (IL-7) is exploited in cancer immunotherapies although its status in solid tumors is largely unknown." (PMID 31185636, 2019). "However, the mechanism of cancer metastasis or growth induced by IL-7 remains controversial, and its role in human clinical conditions is not yet understood." (PMID 31061414, 2019). "Interleukin (IL)-7 is among the cytokines exploited as immunomodulators in cancer immunotherapy." (PMID 31185636, 2019). "Interleukin 7 (IL-7) is a homeostatic cytokine that increases T-cell repertoire diversity through expansion of naive T cells and is being investigated in several malignancies." (PMID 31555284, 2019). "Combining cancer and immune biomarkers could improve cancer detection times, and any predictions that could be made (at least through the use of CA-125/IL-7 biomarkers) are patient specific." (PMID 29554938, 2018). "However, the immune response (which influences the level of secreted IL-7 biomarker) plays an important role in improving and/or delaying cancer detection." (PMID 29554938, 2018). "In this case, the construction of solution diagrams in the space generated by the IL-7 and CA-125 biomarkers could allow us predict the long-term evolution of cancer biomarkers, thus allowing us to make predictions on cancer detection times." (PMID 29554938, 2018). "Besides IL-7, there have been concerted efforts to use the immune system to fight cancer, which has led to study, exploitation and development of other cytokines for cancer immunotherapy." (PMID 29246138, 2017). "However, there is an increasing number of reports showing IL-7 to be overexpressed by solid tumors and being elevated in sera of the cancer patients." (PMID 27866242, 2017). "Augmenting of IL-7 expression is of great importance in cancer immunotherapy." (PMID 29246138, 2017). "In addition, we found that EL upregulated IL-7 gene transcription strongly in A549 lung cells and weakly in several other cancer cell lines." (PMID 27589392, 2016). "It has been described that treatment with IL-2 may increase the amount of regulatory T cells in cancer patients, while IL-7 may have opposite effects." (PMID 25972868, 2015). "Thus, we focused on the application of IL-7 as an immunotherapy for cancer treatment and the action mechanism of IL-7." (PMID 25955647, 2015). "IL-7 fights against the immunosuppressive network to improve immune function on cancer cells." (PMID 25955647, 2015). "Inadequate supply of IL-7 in SLOs might be insufficient to support the survival of activated T cells, thereby aggravating the immunosuppression of cancer." (PMID 25955647, 2015). "IL-7 also induces VEGF-D secretion in cancer cells, suggesting IL-7 may enhance canonical lymphangiogenesis through the VEGF pathway." (PMID 25580369, 2014). "Such drugs as histone deacetylase inhibitors, currently used and licensed for the treatment of some cancers, or activating latently infected resting cells with cytokines, such as IL-7 or prostratin, show promising results in reversing latency in vitro when used either alone or in combination." (PMID 21255462, 2011). "IL-2, IL-7, IL-15 and IL-21 are of particular interest in cancer immunotherapy." (PMID 21943235, 2011). "However, recombinant IL-7 has thus far only been tested in cancer immunotherapy trials in humans." (PMID 39088271, 2024). "Finally, IL-7 and IL-7R play critical roles in the impaired immune systems of patients with cancer." (PMID 39086683, 2023). "Interestingly, certain studies in recent years have found that IL7R may be directly related to cancer; however, the function of IL7 and the IL7R may result in dual outcomes." (PMID 37381714, 2023).
cancer (continued). "The higher concentration of exogenous IL-7 might be sufficient for cellular stimulation in cancers." (PMID 35850640, 2022). "However, the regulatory role of IL-7 might be in a context-specific manner, and might be different in cancers." (PMID 35850640, 2022). "Therefore, the adjuvant value of IL-7 for cancer vaccines is further explored in clinical trials." (PMID 36389666, 2022). "Moreover, IL-7 was clinically well-tolerant for cancer patients." (PMID 36389666, 2022). "We introduced a recombinant Mycobacterium smegmatis (rSmeg-hMIF-hIL-7) vaccine that could deliver a fusion protein of human macrophage migration inhibitory factor (MIF) and interleukin 7, which could act as a target antigen and as an adjuvant of cancer vaccine, respectively." (PMID 34389619, 2021). "Therefore, modulation of IL-7 by proteases secreted by infiltrating leukocytes or cancer cells are a plausible process both in MS and in cancer pathologies and these elements justify further investigation of the functional implications of IL-7 proteolytic processing." (PMID 34276694, 2021). "Indeed, we found that rSmeg-hMIF-hIL-7 elicited an enhanced CTL response against CD4+ and CD8+ T cells cocultured with infected dendritic cells compared with rSmeg expressing h-MIF alone or h-IL-7 alone, suggesting an adjuvant effect of IL-7 in cancer immunotherapy." (PMID 34389619, 2021). "The mechanism could be the ability of IL-7 to restore the naïve T cell pool through increased survival signals or through more homeostatic proliferation; this was also confirmed in clinical trial of rhIL-7 treatment for refractory cancer patients." (PMID 34603318, 2021). "Therefore, recombinant human IL–7 (rhIL-7) has been produced for treating patients with cancer." (PMID 31138762, 2019). "Thus, IL-7 is a promising cytokine for cancer immunotherapy." (PMID 30842774, 2019). "Interleukin‐7 (IL‐7) is a cytokine that has been known since long in immunology, and recent studies found the role of IL‐7 was far beyond the field of immunology and it might have direct or indirect effect on cancer." (PMID 29377588, 2018). "Hence, in the light of these experimental data, persistent elevation of IL-7 observed after RACS may lessen the immunological vulnerability of cancer patients in the perioperative period." (PMID 29904108, 2018). "Also, many cancer-related genes such as IL7, S100B and IER3 showed an altered expression pattern." (PMID 28325946, 2017). "It is unclear whether IL-7 may signal tumors themselves to accelerate the progression of cancer." (PMID 25955647, 2015). "Therefore, elevated plasmatic IL-7 may sustain the increased distribution of CD127lo CCR7−CD45RA−CD8+ T cell and CCR7−CD45RA+CD8+ T cell subsets in the circulation of cancer patients or may be due to that CCR7−CD45RA+CD8+ T cell subsets consumed less IL-7." (PMID 24465587, 2014). "IL-7 involvement in the bone metastasis formation and in the spontaneous osteoclastogenesis of cancer patients adds a further detail to the mechanisms of bone resorption and might be useful to design novel therapeutic approaches for treatment and prevention of bone metastasis." (PMID 17205128, 2006). "Our results suggest the potential of C8A8 in cancer immunotherapy, particularly in NSCLC when combined with IL-7-CAR-T cell therapy." (PMID 41450878, 2025). "Heatmap of the RNA-seq data for the culture cells indicates that expressions of Il7, Serpinb9e, and Slpi genes were significantly upregulated in KEAP1-KO cancer cells, but were downregulated in DKO cancer cells." (PMID 41035689, 2025). "In normal circumstances, immune cells, especially T cells, receive IL-7 signals through CD127, enhancing their survival and functionality to combat abnormal cells, including cancer cells." (PMID 38566827, 2024). "Overall, the results demonstrated that incorporating C5/IL7 into CAR can enhance transduced T cells’ proliferative potential and lead to the development of phenotypes well-suited for successful cancer immunotherapy." (PMID 39450160, 2024).